KEAP1 (kelch like ECH associated protein 1)
Diseases named in the same sentence as KEAP1 in open-access papers (continued):
Sharing a sentence is not in itself a finding about the gene and the disease.
renal fibrosis (13 papers, 2021 to 2026). A final common manifestation of a wide variety of chronic kidney diseases characterized by glomerulosclerosis and tubulointerstitial fibrosis. "Interventions targeting the Kelch-like ECH-associated protein 1 (KEAP1)-Nrf2 pathway are extremely successful in combating the ubiquitous oxidative stress in renal fibrosis." (PMID 40149885, 2025). "Collectively, our study revealed that ISO alleviated renal fibrosis by inducing endogenous H2S and regulating Keap1-Nrf2 interaction through sulfhydration of Keap1." (PMID 39456167, 2024). "In conclusion, our research demonstrates that ISO alleviates renal fibrosis by inducing endogenous H2S and modulating Keap1-Nrf2 interaction through Keap1 sulfhydration." (PMID 39456167, 2024). "Our earlier publication showed that poricoic acids abolished AHR, IƙB/NF-ƙB and Keap1/Nrf2 pathways in mice with renal fibrosis." (PMID 39239643, 2024). "Further investigation revealed that SIRT1 significantly enhanced the activity of the Keap1/Nrf2/ARE pathway to alleviate advanced glycation end-product-induced renal fibrosis." (PMID 39335456, 2024). "In terms of renal fibrosis improvement, TSG significantly diminishes oxidative stress levels by activating the nuclear factor erythroid 2-related factor 2- Kelch-like ECH-associated protein 1(Nrf2-Keap1) antioxidant pathway." (PMID 41347159, 2025). "Activation of the Kelch-like ECH-associated protein 1 (Keap1)/Nrf2/antioxidant response element (ARE) signaling pathway is pivotal in the cellular response to oxidative stress and effectively impedes the progression of renal fibrosis." (PMID 39335456, 2024). "Furthermore, a study uncovers that increased interactions of Keap1 with CUL3 could promote renal fibrosis by reducing Nrf2 level." (PMID 34227919, 2021). "It stimulates miR-200a, downregulates Keap1 expression, activates NRF2, alleviates redox imbalance, and thus anti-renal fibrosis." (PMID 41357857, 2025). "Studies have shown that curcumin can improve oxidative stress status in diabetic rats through the NRF2/KEAP1/ARE pathway and alleviate renal fibrosis." (PMID 39731593, 2024). "Taken together, these results indicated that the activation of the anti-inflammatory and anti-oxidative Keap1/Nrf2 signaling pathway was involved in SKI and three anthraquinones against renal fibrosis in the adenine-induced CRF rats." (PMID 35002735, 2021). "Therefore, our study revealed that activation of the impaired Keap1/Nrf2 signaling pathway might be also a potential molecular mechanism of anti-oxidant and anti-inflammatory bioactivities of both SKI and three anthraquinones against renal fibrosis." (PMID 35002735, 2021).
cardiomyopathy (12 papers, 2017 to 2025). A disease of the heart muscle or myocardium proper. "The Kelch-like ECH-associated protein 1 (Keap1)/NRF2 pathway is activated through oxidative stress in an animal model of DOX-induced cardiomyopathy and myocardial IRI." (PMID 33532140, 2021). "This study revealed a new mechanism by which SMI alleviates DOX-induced 45 cardiomyopathy by modulating the Nrf2/Keap1 signal pathway." (PMID 35298357, 2022). "Evidence that aberrant cardiac remodeling is attenuated by a variety of Nrf2 target genes such as SOD, HO-1 and glutathione peroxidase (GPx) has motivated investigation into a possible protective role of the Nrf2/Keap1/ARE pathway against cardiomyopathy in DM." (PMID 28913364, 2017). "Our previous research demonstrated that phloretin promotes the dissociation of the Keap1/Nrf2 complex, facilitating Nrf2 nuclear translocation, consistent with reports that phloretin prevents cardiomyopathy by inhibiting oxidative stress through Keap1/Nrf2 complex dissociation." (PMID 41354995, 2025). "Methylation changes in genes like KEAP1 and LXRɑ affecting cardiomyopathy progression." (PMID 38323108, 2024). "Although it remains challenging to translate these findings on animal models to late‐onset Dox‐induced cardiomyopathy in humans, the activity of Keap1/Nrf2 signaling may have a central role in determining cell fate and clinical outcomes." (PMID 37679058, 2023). "Another study on cardiomyopathy revealed that TMBIM1 deficiency exacerbated the inflammation and oxidative stress induced by high fat diet by reducing Nrf2 and Ho-1 while increasing Keap-1 expression in mice." (PMID 34924003, 2021). "As ZJ01 is an effective Keap1–Nrf2 PPI inhibitor, we speculated ZJ01 might inhibit LPS-induced cardiomyopathy through disrupting Keap1–Nrf2 PPI which could induce Nrf2 nuclear accumulation and thus blocking oxidative and inflammatory signalling." (PMID 29693453, 2018). "However, chronic overactivation of the Nrf2/Keap1/ARE signaling pathway may actually contribute to cardiomyopathy, which undermines the encouraging results of acute Nrf2 induction." (PMID 28913364, 2017). "In the present study, we describe the identification of ZJ01 as a new Keap1–Nrf2 PPI inhibitor and further investigate its in vitro and in vivo cytoprotective effects on LPS-induced cardiomyopathy." (PMID 29693453, 2018). "With the development of the structural and mechanistic knowledge of the Keap1-Nrf2 system, various Keap1-Nrf2 PPI inhibitors have been developed as potential therapeutics against chronic and inflammatory conditions, including pulmonary inflammation, cardiomyopathy and myocarditis." (PMID 31279986, 2019).
chronic kidney disease (12 papers, 2018 to 2026). Impairment of the renal function secondary to chronic kidney damage persisting for three or more months. "In chronic kidney disease patients, a cohort carrying the A allele in the rs11085735 polymorphism located in the proximity of exon 3 of KEAP1 was defined as an independent predictor of incident cardiovascular events." (PMID 35326157, 2022). "Previously, using an experimental model of chronic kidney disease (CKD) by renal ablation we observed an antioxidant effect of allicin by a mechanism dependent on the nuclear factor erythroid 2-related factor 2/Kelch ECH associating protein 1 (Nrf2/Keap1) pathway." (PMID 30314265, 2018). "Oxidative stress is a key pathogenic pathway in chronic kidney disease (CKD), and research in nephrectomized animals indicates that the KEAP1/NRF2 pathway is impaired in CKD, with marked elevation of KEAP1 levels and a decline in NRF2 activity." (PMID 37962746, 2024). "An animal study has shown that the impact of curcumin in the treatment of chronic kidney disease (CKD) is mediated via the Keap1/Nrf2 axis." (PMID 35053230, 2022). "In addition, one study found that in the renal tubules after acute kidney injury, glycogen synthase kinase 3β (GSK-3β) overactivity impaired NRF2 antioxidant response via a KEAP1-independent mechanism, resulting in persistent oxidative damages that lead to chronic kidney disease (CKD)." (PMID 35721561, 2022). "Experimental models of chronic kidney disease such as diabetic nephropathy, subtotal nephrectomy, and unilateral ureteral obstruction showed decreased NRF2 nuclear translocation along with increased KEAP1 levels." (PMID 35052660, 2022). "Apoptosis is a factor that promotes vascular calcification in patients with chronic kidney disease (CKD), and MitoQ inhibits vascular calcification by suppressing apoptosis of vascular smooth muscle cells (VSMC) via the Keap1/Nrf2 pathway." (PMID 35313524, 2022).
head and neck cancer (12 papers, 2019 to 2025). A primary or metastatic malignant neoplasm affecting the head and neck. "In this study, we set out to explore the impact of Keap1/Nrf2 mutations in HN-CSCs and assess the differences in tumor behaviors and clinical outcomes in head and neck cancer." (PMID 37894373, 2023). "Cancerous HN-CSCs and benign stem cells were obtained from freshly resected head and neck cancer patients (n = 50) via flow cytometry cell sorting and tested for Keap1/Nrf2 mutations." (PMID 37894373, 2023). "Patients with head and neck cancer whose tumor exhibits Keap1/Nrf2 mutations in their stem cells are significantly more likely to develop rapid lung metastasis and fail treatment." (PMID 37894373, 2023). "Although mutations in the Keap1/Nrf2 pathway have been reported in 4–5% of head and neck cancer primary tumors, their existence in HN-CSCs and possible clinical implications have not been investigated." (PMID 37894373, 2023). "The prognostic significance of Keap1/Nrf2 signaling pathway mutations in head and neck cancer remains mostly unexplored." (PMID 37894373, 2023). "The rationale behind our hypothesis was that patients with head and neck cancer whose tumors carry Keap1/Nrf2 mutations in HN-CSCs are more likely to develop lung metastases." (PMID 37894373, 2023). "Thus, Keap1/Nrf2 pathway mutations in HN-CSC are strongly associated with poor outcomes with treatment failure in head and neck cancer." (PMID 37894373, 2023). "The results from this study provide credence to the idea that analysis of both HN-CSCs and the evaluation of the head and neck cancer tumors might be useful for better treatment strategies in patients who harbor Keap1/Nrf2 mutations in HN-CSCs." (PMID 37894373, 2023). "Mutations in Keap1/Nrf2 in head and neck cancer result in abnormal cell growth." (PMID 37894373, 2023). "In our case, only 2 of 13 patients (16%) in the tumor without HN-CSC group had lung metastasis but had a better therapeutic response, suggesting that Keap1/Nrf2 mutations in HN-CSCs may be partially responsible for head and neck cancer lung metastasis and the least therapeutic outcome." (PMID 37894373, 2023). "Thus, overexpression of Nrf2 due to Keap1 loss may confer resistance to cisplatin, a widely used chemotherapy regimen for head and neck cancer, by regulating ROS and cancer stem cell pathways." (PMID 35945195, 2022). "Apart from these, several oncogenes in the Keap1/Nrf2 signaling pathway have been identified in head and neck cancer." (PMID 37894373, 2023). "Recent studies, including ours, have shown that the Keap1/Nrf2 pathway contributes to the development and progression of head and neck cancer." (PMID 37894373, 2023). "Previous studies also found that ART induces the expression of HO-1 by degrading Keap1 in head and neck cancer cells (HNC) as well as in mice." (PMID 37760834, 2023). "Recently, we have reported that Nrf2 overexpression due to Keap1 alterations had a poor prognosis, overall shorter survival, and therapeutic failure in head and neck cancer." (PMID 37894373, 2023). "Skipping of exon 2 and both exon 2 and 3 of NFE2L2 gene was shown to occur in lung and head and neck cancers to produce constitutively active Nrf2 forms resistant to Keap1-mediated degradation." (PMID 34063559, 2021). "The skipping of exon 2 that encodes these motifs or exons 2+3 in NFE2L2 gene was observed in lung and head and neck cancers, resulting in Nrf2 forms resistant to Keap1-mediated degradation." (PMID 34063559, 2021). "Keap1 loss-of-function and/or Nrf2 gain-of-function mutations were predictors of poor clinical outcome in different tumour aetiologies, such as in HCC, and ovarian, lung, endometrial, breast, and head and neck cancers." (PMID 36142252, 2022).
chronic obstructive pulmonary disease (11 papers, 2018 to 2025). A chronic and progressive lung disorder characterized by the loss of elasticity of the bronchial tree and the air sacs, destruction of the air sacs wall, thickening of the bronchial wall, and mucous accumulation in the bronchial tree. "Isorhamnetin mainly affects Nrf2/Keap1 pathway and significantly alleviates the inflammatory response in chronic obstructive pulmonary disease (COPD) mice." (PMID 39484157, 2024). "In COPD (chronic obstructive pulmonary disease) patients, it was observed that Keap1 changed its conformation due to a long-term stimulation by free radicals or other chemicals in tobacco, leading to abnormal expression of the Keap1-Nrf2 pathway." (PMID 38634043, 2024). "Evidence has shown their capability to increase the expression of NRF2 target genes in cellular and in vivo models of chronic obstructive pulmonary disease (COPD), and to interfere with the direct PPI between KEAP1 and NRF2 or the PPI between KEAP1 and CUL3." (PMID 34663413, 2021). "Moreover, three in vivo studies showed that AST administration inhibited the development of chronic obstructive pulmonary disease (COPD) and acute lung injury through activation of Nrf2 and, accordingly, promoted HO-1 and inhibited Keap1." (PMID 35056816, 2022). "In a chronic obstructive pulmonary disease (COPD) mouse model, CPT alleviated lung injury by activating the Keap1/Nrf2 pathway to reduce ROS levels, suppress NF-κB signaling, and lower TNF-α concentrations in pulmonary tissue serum, thereby mitigating inflammation." (PMID 41154678, 2025).
COVID-19 (11 papers, 2021 to 2025). A disease caused by infection with severe acute respiratory syndrome coronavirus 2. "Our results showed that NFE2L2 rs2364723C>G allele G had a protective effect against severe COVID-19, while KEAP1 rs9676881A>G allele G and rs34197572C>T minor allele T were associated with more aggressive stages of COVID-19." (PMID 36613859, 2022). "The observed reduction in the level of free Keap1 in the granulocytes of patients who died from COVID-19 was associated with a significant increase in Nrf2 levels, which, in turn, promotes increased transcriptional activity of Nrf2 manifested in increased HO-1 levels." (PMID 37686388, 2023). "Our identification of KEAP1 through splicing regulation in heart tissue and transcriptomic-phenotype association with cholesterol traits aligns with the hypothesized role of cholesterol in COVID-19 pathogenicity." (PMID 34315903, 2021). "Our results constitute one of the first pieces of evidence of the relationship of NFE2L2 (rs2364723C/G) and KEAP1 (rs9676881A/G; rs34197572C/T) with COVID-19." (PMID 36613859, 2022). "At the genetic level, COVID-19 hospitalization and MS share five risk genes within two loci, including TNFAIP8, HSD17B4, CDC37, PDE4A, and KEAP1, which may mediate the association between MS and COVID-19." (PMID 37395896, 2023). "SNP NRF2 rs2364723C>G allele G demonstrated a protective effect against severe COVID-19, while KEAP1 SNP rs9676881A>G allele G and rs34197572C>T minor allele T were associated with more aggressive stages of COVID-19." (PMID 36613859, 2022). "Furthermore, the transcriptome-wide analysis identified six novel loci, among others, consisting of genes—IFIT3, KEAP1, and GNL3 demonstrating their putative association with COVID-19 hospitalization outcome." (PMID 34315903, 2021). "Therefore, Nrf2 activators and KEAP1 inhibitors may alleviate OS and inflammatory changes and prevent cytokine storm development in COVID-19." (PMID 37796433, 2023). "The KEAP1/NRF2 pathway, the major redox-responsive pathway, has emerged as a potential therapeutic target for COVID-19 as it regulates redox homeostasis and inflammation that are altered during SARS-CoV-2 infection." (PMID 39334742, 2024). "This may be related to the fact that the Nrf2 inhibitor complex, i.e., Keap1/Cul3, can direct IκBα to ubiquitination and degradation, and in patients who did not survive COVID-19, the level of Keap1 showed a downward trend." (PMID 37686388, 2023).
esophageal squamous cell carcinoma (11 papers, 2017 to 2026). Esophageal squamous cell carcinoma (ESCC) is a type of esophageal carcinoma (EC) that can affect any part of the esophagus, but is usually located in the upper or middle third. "In esophageal squamous cell carcinoma, methylseleninic acid activated KEAP1/NRF2 pathway via upregulating miR-200a, the latter inhibited KEAP1 expression and induced expression of NRF296." (PMID 32709863, 2020). "The CRISPR/Cas9 system was used to prove the direct binding to the coding region of KEAP1 by miR-432-3p in the esophageal squamous cell carcinoma (ESCC)." (PMID 29643973, 2018). "In addition, mir-432-3p has also been found to inhibit Keap1 expression in ESCC (esophageal squamous cell carcinoma), which in turn regulates the antioxidant activity of the Keap1-Nrf2 pathway." (PMID 38634043, 2024). "Similarly, miR-432-3p was found to impair Keap1 mRNA translation in esophageal squamous cell carcinoma, positively modulating Nrf2 activity, while increased levels of miR-200a promoted Keap1 degradation and Nrf2 stabilization in OB-6 osteoblastic cells." (PMID 34573095, 2021). "miR-432-3p binds directly to the KEAP1 coding region, downregulating it and upregulating the transcription of downstream genes of the NRF2–ARE pathway in esophageal squamous cell carcinoma." (PMID 32492865, 2020). "miR-200a binds to the KEAP1 3′UTR sequence leading to the degradation of its mRNA in breast cancer cell, hepatocellular carcinoma cells, and esophageal squamous cell carcinoma cells." (PMID 32492865, 2020). "A direct inhibition effect of miR-200a on KEAP1 was elucidated in human MDA-MB-231 and Hs578T breast and esophageal squamous cell carcinoma cells under methylseleninic acid (MSA) treatment." (PMID 29643973, 2018).
Hypertension (11 papers, 2013 to 2025). The presence of chronic increased pressure in the systemic arterial system. "Kelch-like ECH-associated protein 1 (Keap1), an intracellular inhibitor of Nrf2, exhibits elevated levels of hypertension." (PMID 38791545, 2024). "Our findings are partly supported in a study of mice with pregnancy-associated hypertension where KEAP1 knockdown resulted in reduced fetal weight, and reduced placental angiogenesis stimulated by increased ROS production was suggested as a causative mechanism." (PMID 35216082, 2022). "Prior studies have shown that peptides with high hydrophobicity can effectively prevent oxidation and hypertension by binding to Keap1 and ACE, respectively." (PMID 40077777, 2025). "This review explores the potential role of the lncRNA MALAT1 in controlling the Keap1-Nrf2-antioxidant defense pathway in salt-induced hypertension." (PMID 38791545, 2024). "URB597 administrated to rats with spontaneous hypertension decreased the expression of cardiac Nrf2, HO-1, Keap1, Bach1, and KAP1; increased expression of kinases ERK1/2 and MAPK; while p21, p62, and p38 amounts were not changed." (PMID 30223427, 2018). "Spontaneous hypertension led to an increase in the expression of Nrf2 inhibitors, such as Keap1 and Bach1 in the heart." (PMID 30223427, 2018). "Recently, we reported that allicin treatment improved cardiac dysfunction and decreased hypertension, vascular reactivity to Ang II, and the oxidative stress in a way dependent on the Nrf2/Keap1 system." (PMID 28926934, 2017). "Thus, MALAT1, acting via the Keap1-Nrf2 pathway, modulates antioxidant defense in hypertension." (PMID 38791545, 2024). "The anti-hypertension mechanism of the agent was related with dual bioactivities of ACE inhibition and antioxidant involving NADPH oxidase and Keap1/Nrf2 signaling pathways." (PMID 38933890, 2024). "In this review, we have compiled a body of evidence to examine the impact of MALAT1 on hypertension and CVD, elucidating its roles in inflammation responses and mechanistic approach via the Keap1-Nrf2 pathway modulates antioxidant defense in salt-sensitive hypertension." (PMID 38791545, 2024). "In this study, Western blot analysis showed that SRP inhibited Keap1 expression and enhanced the dissociation of Nrf2 into the nucleus to express antioxidant genes, the results demonstrated that SRP was an effective agent in hypertension related with oxidative stress." (PMID 38933890, 2024).